PROM2 (prominin 2)
Diseases named in the same sentence as PROM2 in open-access papers (continued):
Sharing a sentence is not in itself a finding about the gene and the disease.
pancreatic cancer (2 papers, 2020 to 2023). "As further evidence, we show PROM2 expression and Akt phosphorylation both promote gemcitabine chemoresistance, and cause poorer survival in clinical samples with pancreatic cancer." (PMID 32123287, 2020). "We also found higher PROM2 expression is associated with shortened overall and disease-free survival times in patients diagnosed with pancreatic cancer." (PMID 32123287, 2020). "In addition, the overexpression of PROM2 indicates stronger resistance to gemcitabine and causes higher relapse rates in patients with pancreatic cancer." (PMID 32123287, 2020). "Here we showed that PROM2 is overexpressed in pancreatic cancer and positively correlated with overall and disease-free survival of PDAC patients." (PMID 32123287, 2020). "Researchers in China led by Jian Sun at Sun Yat-Sen University, Guangzhou, investigated the role of PROM2 in cultured human pancreatic cancer cells and in a mouse model of pancreatic cancer." (PMID 32123287, 2020). "In this study, we aimed to unravel the potential role(s) of PROM2 in pancreatic cancer progression and development of chemoresistance to gemcitabine." (PMID 32123287, 2020). "In conclusion, PROM2 knockdown augments the chemosensitivity of pancreatic cancer cells to gemcitabine treatment." (PMID 32123287, 2020). "Statistical analysis confirmed that the expression of PROM2 was significantly correlated with clinical stages in patients with pancreatic cancer, and also indicated lower overall survival and disease-free survival rates." (PMID 32123287, 2020). "Consistently, both the mRNA and protein expression level of PROM2 were markedly increased in pancreatic cancer cell lines compared with immortal pancreatic ductal epithelial cell (HPDECs)." (PMID 32123287, 2020). "Therefore, our results offer new insight into both the biological function and molecular regulation of PROM2, rendering PROM2 a prominent oncogene involved in the chemoresistance of pancreatic cancer." (PMID 32123287, 2020). "Importantly, PROM2 was significantly upregulated in eight freshly collected pancreatic cancer tissues before gemcitabine-based treatment compared to two adjacent pancreatic tissues N1–N2." (PMID 32123287, 2020). "Similarly, downregulation of PROM2 lowered the IC50 value of gemcitabine in pancreatic cancer cell lines." (PMID 32123287, 2020). "Overall, our in vivo data indicate PROM2 promotes chemoresistance in pancreatic cancer." (PMID 32123287, 2020). "A cell membrane protein called PROM2 promotes the resistance of pancreatic cancer to the anti-cancer drug gemcitabine, suggesting PROM2 and the molecular signaling pathway it stimulates could be targeted by new treatments." (PMID 32123287, 2020). "In addition, overexpression of PROM2 in pancreatic cancer cells augments gemcitabine chemoresistance, both in vivo and in vitro." (PMID 32123287, 2020). "We show PROM2, a transmembrane glycoprotein, is ubiquitously upregulated in pancreatic cancer cell." (PMID 32123287, 2020). "Collectively, these data demonstrate PROM2 overexpression is in a close relationship with pancreatic cancer progression, and could serve as an independent prognostic factor." (PMID 32123287, 2020). "Our data indicate PROM2 enhanced gemcitabine chemoresistance in vitro and in vivo, which implies that PROM2 could serve as a biomarker for co-therapy of gemcitabine and Akt inhibitors in pancreatic cancer treatment." (PMID 32123287, 2020). "The expression of PROM2 and p-AKT proteins was positively correlated in pancreatic cancer tissues (P = 0.022, r = 0.688)." (PMID 32123287, 2020). "To better define whether PROM2 is clinically correlated with the Akt signaling pathway, we examined the expression levels of PROM2 and AKT in 10 freshly collected pancreatic cancer tissues." (PMID 32123287, 2020). "Downregulation of PROM2 did not change the colony formation ability of AsPC-1 and Hs 766T pancreatic cancer cell lines without gemcitabine treatment." (PMID 32123287, 2020).
pancreatic cancer (continued). "However, the biological function of PROM2 has not yet been verified and its role in pancreatic cancer is unclear." (PMID 32123287, 2020).
prostate carcinoma (2 papers, 2010 to 2020). A carcinoma that arises from epithelial cells of the prostate gland. "Our data also suggest that prominin-2 could be an interesting new marker for prostate cancer TICs." (PMID 20500816, 2010). "Furthermore, we propose new candidate prostate TIC markers (PROM2 and SOX9) as well as potential biomarkers for prostate cancer status and progression that may be related to the TIC phenotype." (PMID 20500816, 2010).
skin cancer (2 papers, 2020 to 2023). "PROM2 mutations were mainly found in skin cancers and predominantly consisted of point mutations of a hotspot at position p.Q508R and p.R582Q/W in the prominin domain." (PMID 31164716, 2020). "To investigate the relationship between prognosis and co-expression of PROM1 and PROM2, we retrieved clinical prognosis data from patients with various types of cancers, including breast, kidney, brain, ovarian, lung, and skin cancers, using OncoLnc, which accesses data from TCGA." (PMID 31164716, 2020). "Unlike PROM1, PROM2 mutations primarily occurred in skin cancer." (PMID 31164716, 2020).
triple-negative breast carcinoma (2 papers, 2024 to 2025). An invasive breast carcinoma which is negative for expression of estrogen receptor (ER), progesterone receptor (PR), and human epidermal growth factor receptor 2 (HER2). "PROM2 has previously been associated with chemoresistance and membrane remodeling in triple-negative breast cancer, but a few studies to date has characterized its expression or function in OC." (PMID 40826138, 2025). "Using PDXs of human renal cell carcinomas and triple negative breast cancers, we assessed PROM2 and EMT marker mRNA expression." (PMID 38515278, 2024).
Alzheimer disease (1 paper, 2020). A progressive, neurodegenerative disease characterized by loss of function and death of nerve cells in several areas of the brain leading to loss of cognitive function such as memory and language. "The Alzheimer disease-amyloid secretase pathway was the most significant pathway associated with the PROM1-correlated gene, whereas the EGF receptor signaling pathway was the key player in the PROM2-correlated gene cluster." (PMID 31164716, 2020).
ciliopathy (1 paper, 2021). A genetic disorder of the cellular cilia or the cilia anchoring structures, the basal bodies, or of ciliary function. "This bio-informatics approach unveils yet undescribed cilia and ciliopathy genes associated with COPD including NEK6 and PROM2 that may contribute to the pathology, and suggests a COPD endotype exhibiting ciliopathy features (CiliOPD)." (PMID 33639936, 2021).
endometrial cancer (1 paper, 2024). Primary or metastatic malignant neoplasm involving the endometrium (mucous membrane that lines the endometrial cavity). "Moreover, the knockdown of PROM2 has been observed to promote apoptosis in endometrial cancer cell lines." (PMID 39079132, 2024). "Research findings indicate that inhibiting PROM2 expression results in heightened sensitivity to paclitaxel, leading to decreased IC50 values and reduced proliferation in endometrial cancer." (PMID 39079132, 2024).
heart failure (1 paper, 2025). Inability of the heart to pump blood at an adequate rate to meet tissue metabolic requirements. "Elevated PROM2 levels are observed in aged mouse hearts and in the atria of patients with heart failure with preserved ejection fraction (HFpEF)." (PMID 40869128, 2025).
lung adenocarcinoma (1 paper, 2019). A carcinoma that arises from the lung and is characterized by the presence of malignant glandular epithelial cells. "In addition, factors previously identified to be specific markers of lung adenocarcinoma were upregulated, including PROM2, CLDN3, and TJP3, as were genes proposed to have potential diagnostic or prognostic value in human cancers, including MMP9, AGR2, SULF1, NHSL1, LGR5, MUC1, and PIK3C2G." (PMID 31434729, 2019).
metastatic disease (1 paper, 2024). "Our results, providing a new model to study metastatic disease, open the way for further studies using PROM2 as a bio‐target in resort situations in human metastatic melanoma and also in other cancer types." (PMID 38515278, 2024).
metastatic melanoma (1 paper, 2024). A melanoma that has spread from its primary site to another anatomic site. "In this study, we demonstrated that the runaway metastatic process is closely linked to PROM2 overexpression, making PROM2 a promising bio‐target in resort situations in metastatic melanoma, and also possibly in other cancer types." (PMID 38515278, 2024). "We also demonstrated that PROM2 was implicated in an aggravation loop, contributing to increase the metastatic burden both in murine metastatic models and in patients with metastatic melanoma." (PMID 38515278, 2024). "Our results open the way for further studies using PROM2 as a bio‐target in resort situations in human metastatic melanoma and also in other cancer types." (PMID 38515278, 2024). "In this translational study, we set out to decipher the biological roles of PROM2 during the metastatic process and resistance to cell death, in particular for metastatic melanoma." (PMID 38515278, 2024). "In this translational study, we set out to decipher the biological roles of PROM2 during the metastatic process, in particular for metastatic melanoma." (PMID 38515278, 2024). "We thus confirmed our hypothesis that in human metastatic melanoma PROM2 appears to be the cornerstone of two cancer hallmarks: the metastatic process and resistance to ferroptotic cell death." (PMID 38515278, 2024).
myocardial infarction (1 paper, 2025). Gross necrosis of the myocardium, as a result of interruption of the blood supply to the area, as in coronary thrombosis. "This stands in contrast to the LAD‐induced myocardial infarction model, in which BubR1 downregulation coincides with Prom2 upregulation, indicative of cardiomyocyte senescence." (PMID 40607964, 2025).
cancer (13 papers, 2015 to 2025). A tumor composed of atypical neoplastic, often pleomorphic cells that invade other tissues. "Although both CD63 and PROM2 are implicated in mitigating ferroptosis through EV-mediated ferritin expulsion in various cancer models, indeed, their regulation is different." (PMID 40177133, 2025). "We then intended to demonstrate the link between PROM2 expression and a second cancer hallmark that is resistance to cell death." (PMID 38515278, 2024). "In our systematic analysis, we also found several missense and truncating mutations within PROM1 and PROM2 protein-coding sequences, especially in the prominin domain, in various cancer types." (PMID 31164716, 2020). "Therefore, we investigated the patterns of expression, mutation, and copy number alteration of PROM1 and PROM2 genes to determine their clinical significance in human cancers through systematic data analysis." (PMID 31164716, 2020). "Prominin 2 (PROM2) has also been associated with certain cancers." (PMID 31164716, 2020). "Quantitatively, TMED10 and PROM2 silencing reduced proliferation to approximately 55–60% of the control levels (***P < 0.001), indicating a strong inhibitory effect on cancer cell growth." (PMID 40826138, 2025). "PROM2 was amongst those downregulated and is of significant interest as its prognostic value in cancer is controversial, with its underexpression potentially providing benefit to drug-resistant cells." (PMID 40946111, 2025). "In more recent years, Prom2 has been identified as a new marker of cancer cells, conferring tumorigenicity and resistance to chemotherapy." (PMID 38757782, 2024). "We found an inverse correlation between tumour PROM2 expression and ferrous iron levels and also between PROM2 expression and lipid peroxidation, in both cancer types." (PMID 38515278, 2024). "Using laser‐microdissection to select cancer cells, combined with ddPCR, we found that PROM2 and EMT marker expression gradually increased with the metastatic progression in these three patients." (PMID 38515278, 2024). "We also analyzed the interacting partners and genes co-expressed with PROM1 and PROM2 in various cancers and subsequently, analyzed these genes to predict the probable underlying signaling pathways involved." (PMID 31164716, 2020). "The clinical prognosis data were then used to prepare a multivariate survival plot to assess the effect of high/high, high/low, low/high, and low/low expression of PROM1 and PROM2 in each cancer." (PMID 31164716, 2020). "To identify genes that correlate with PROM1 and PROM2 expression in selected cancers, we performed a systematic analysis using the R2 platform." (PMID 31164716, 2020). "Production and activity of PROM2 were increased in cancer cells, leading to increased resistance to gemcitabine." (PMID 32123287, 2020). "Despite this research, studies on PROM2 expression in cancer and its relevance to clinical outcomes are still limited." (PMID 31164716, 2020). "Based on the varying characteristics of prominins, we conclude that PROM1 and PROM2 expression differentially modulates the clinical outcomes of cancers." (PMID 31164716, 2020). "While PROM1 is broadly reported and recognized as a marker for cancer stem cells, few studies have investigated the biological function of PROM2." (PMID 32123287, 2020). "The prognostic value of PROM1 and PROM2 expression levels for different cancer patients was also determined based on data from the PrognoScan database." (PMID 31164716, 2020). "To determine the utility of PROM1 and PROM2 as markers of cancer prognosis, we performed a systematic data analysis of numerous gene expression datasets with clearly defined distinguishing parameters between cancer and normal tissues." (PMID 31164716, 2020). "Our data suggest PROM2 is dramatically and ubiquitously upregulated in cancer tissues and cell lines, and leads to shorter overall and disease-free survival time." (PMID 32123287, 2020).
cancer (continued). "The pattern of PROM2 expression in different types of cancers was considerably different to the expression pattern of PROM1." (PMID 31164716, 2020). "To assess the impact of PROM1/PROM2 co-expression on various cancers, we performed several multivariate survival analyses on OncoLnc, using TCGA data." (PMID 31164716, 2020). "Concerning the regulatory mechanisms of Prom2 transcription, the activation of p38MAP kinase has been implicated in the phosphorylation and activation of the Heat Shock transcription factor HSF1 to drive Prom2 upregulation in cancer cells." (PMID 38757782, 2024). "Since PROM2 appears to be the cornerstone of two cancer hallmarks, we wondered whether the combination of these two hallmarks, by way on an aggravation loop, contributes to increasing the metastatic burden." (PMID 38515278, 2024). "Mechanistically, reduced iron concentration in cells caused by PROM2 could protect tumors from ferroptosis, and the inhibition of PROM2 transcription sensitizes drug-resistant cancer cells to ferroptosis inducers." (PMID 35692844, 2022). "The prognostic role of Prominin 2 (PROM2) in human cancers is controversial." (PMID 35692844, 2022). "PROM2 plays an important role in the manipulation of ferritin-mediated iron export, which could modify ferroptosis sensitivity of cancer cells." (PMID 34728613, 2021). "Furthermore, we identified genes that correlated with PROM1 and PROM2 in certain cancers, based on their levels of expression." (PMID 31164716, 2020). "PROM1 and PROM2 were found to be differentially expressed in many cancer types." (PMID 31164716, 2020). "In addition, a short list of three genes was identified that negatively correlated with PROM2 in all cancers analyzed." (PMID 31164716, 2020). "Thus, our multivariate survival analyses showed that the pattern of PROM1 and PROM2 co-expression modulated the clinical outcomes of patients with certain types of cancers, which may help our understanding of the underlying mechanism of cancer prognosis with respect to prominin expression." (PMID 31164716, 2020). "For PROM2, a relatively fewer number of correlated genes were detected in cervical, lung, ovarian, and pancreatic tumors, among which 94 genes were common in all cancers." (PMID 31164716, 2020). "Therefore, the R2 genomics platform was used to identify genes correlated with PROM1 and PROM2 in certain cancers in which these prominins are highly expressed." (PMID 31164716, 2020). "Correspondingly, biocompatible hybrid nanoparticles composed of ferroptosis inducers and PROM2 siRNAs efficiently decreased iron efflux and overcome ferroptosis resistance in cancer cells, indicative of an attractive strategy for ferroptosis-based cancer therapy." (PMID 39346540, 2024). "This correlation analysis suggested that PROM1 and PROM2 perform different functions with respect to pathway regulation; however, they may have some similar functions in certain signaling pathways, in certain cancer types." (PMID 31164716, 2020). "We found a correlation between PROM2 expression and the three EMT markers ZEB1, SNAI1 and TWIST1 in both cancer types." (PMID 38515278, 2024). "In contrast, three fusions, PROM2-KCNIP3, BAIAP2L2-SLC16A8, and D2HGDH-GAL3ST2 had higher expression in the two cancer cell lines than in RWPE-1 cells." (PMID 25658338, 2015). "Furthermore, IHC analysis of PROM2 expression in MIBC, NMIBC, and normal bladder tissues and Western blot analysis of PROM2 expression in BLCA and para-cancer tissues from the FUSCC cohort showed consistent with TCGA results." (PMID 34728613, 2021). "The co-expression (high/high), partial co-expression (low/high), and lack of co-expression (low/low) of PROM1/PROM2 were associated with skin, KIRC, and KIRP cancers, respectively." (PMID 31164716, 2020). "PROM1 and PROM2 were found to be differentially expressed in cancer and normal tissues." (PMID 31164716, 2020).